S100A9 (S100 calcium binding protein A9)
Diseases named in the same sentence as S100A9 in open-access papers (continued):
Sharing a sentence is not in itself a finding about the gene and the disease.
dental caries (2 papers, 2018). The decay of a tooth, in which it becomes softened, discolored, and/or porous. "Protein S100-A9 is a calcium- and zinc-binding protein with a prominent role in regulating the immune response and antimicrobial humoral response, and has also been reported to be associated with dental caries." (PMID 30359274, 2018). "As a result of MRM, protein S100 A9, protein S100 P, coronin 1A and alpha-2-macroglobulin were shared in HDC vs NDC and HDC vs LDC with higher expression levels in HDC group, indicating their potential diagnostic values in the childhood dental caries." (PMID 29351798, 2018).
dermatophytosis (2 papers, 2022 to 2024). A common fungal infection of the stratum corneum of the skin, hair, or nails by a dermatophyte. "Zero of five non-lesional domestic shorthair cats exhibited epidermal immunolabeling for S100A8/S100A9 (calprotectin) while ten of ten cats (5 domestic shorthair cats and 5 Persian cats) with dermatophytosis exhibited moderate to strong, multifocal to diffuse epidermal immunolabeling." (PMID 35157719, 2022).
disc degeneration (2 papers, 2021 to 2025). "Inhibition of S100A9 has been shown to alleviate both disc degeneration and associated inflammatory pain, underscoring its potential as a therapeutic target in DDD." (PMID 40806719, 2025). "Inhibition of the pro‐apoptotic, pro‐degradation and pro‐inflammatory effects of S100A9 on NP cells may be a therapeutic strategy to slow disc degeneration." (PMID 33734570, 2021).
dyslipidemia (2 papers, 2017 to 2025). "Further research is needed to explore whether targeting S100A8 and S100A9 could mitigate dyslipidemia and reduce cardiovascular risk in patients with AD." (PMID 40191205, 2025). "Studies have shown that S100A8- and S100A9-mediated inflammation can alter hepatic lipid metabolism by increasing lipogenesis and decreasing cholesterol efflux, contributing to dyslipidemia." (PMID 40191205, 2025). "In our study, AD-like model mice exhibited elevated serum S100A8 and S100A9 levels along with dyslipidemia, suggesting an interplay between inflammation and lipid metabolism." (PMID 40191205, 2025). "Cessation of AD induction resulted in S100A8 and S100A9 downregulation and improved dyslipidemia." (PMID 40191205, 2025).
fungal infection (2 papers, 2013 to 2021). "Given that S100A9 exerts an antimicrobial activity, probably by chelation of zinc essential for the growth of bacteria and fungi, METTL9-mediated S100A9 methylation might be involved in the innate immune response to bacterial and fungal infection." (PMID 34562450, 2021).
HIV-1 infection (2 papers, 2013 to 2020). The type species of lentivirus and the etiologic agent of acquired immunodeficiency syndrome (AIDS). "In particular, it was shown that HIV-1 infection modulates S100A9 expression on the surface of the monocyte-derived dendritic cells." (PMID 33414815, 2020). "We also tested the impact of the interaction CD85j/S100A9 in the NK cell-mediated control of HIV-1 infection in purified autologous CD4+ T cells by pre-stimulating NK cells with exogenous S100A9 proteins." (PMID 24156302, 2013). "Here, S100A9 tetramer-stimulated NK cells appeared to have a better capacity to control HIV-1 infection than unstimulated NK cells." (PMID 24156302, 2013). "The surface expression of S100A9 was increased on MDDC in response to HIV-1 infection, whereas surface expression levels of S100A8 and S100A8/S100A9 were both decreased." (PMID 24156302, 2013). "We observed that S100A9, a calcium-binding protein of the S100 family, is expressed by MDDC in response to HIV-1 infection and is potentially implicated in the anti-HIV-1 activity of human NK cells through the CD85j ligation and signalisation." (PMID 24156302, 2013). "We further demonstrated that HIV-1 infection of MDDC induces a modulation of S100A9 expression on surface of the MDDC, which potentially influences the anti-HIV-1 activity of human NK cells through a mechanism involving CD85j ligation." (PMID 24156302, 2013). "CD85j is highly expressed on other innate cells, such as monocytes and dendritic cells, and also on B cells, therefore it is possible that CD85j/S100A9 interaction plays a role in the modulation of the activity of those cells during HIV-1 infection." (PMID 24156302, 2013). "Thus, the interactions between CD85j and S100A9 proteins are likely to occur during the early phase of HIV-1 infection characterised by excessive inflammatory responses through NK/DC crosstalk." (PMID 24156302, 2013). "Additionally, we showed that stimulation of NK cells with exogenous S100A9 enhances the control of HIV-1 infection in CD4+ T cells." (PMID 24156302, 2013). "Overall, a productive HIV-1 infection of MDDC was needed to induce changes in the surface expressions of S100A8, S100A9 and S100A8/S100A9 on p24-MDDC." (PMID 24156302, 2013). "We demonstrated that in vitro HIV-1 infection of MDDC induces a modulation of S100A8, S100A9 and S100A8/S100A9 surface expression." (PMID 24156302, 2013). "Pre-stimulation of NK cells by S100A9 monomers induced no change in viral replication; neither S100A8 pre-stimulation had an effect in the control of HIV-1 infection (data not shown)." (PMID 24156302, 2013).
hospital-acquired infections (2 papers, 2014 to 2023). "Our research group has also shown that S100A9 mRNA is increased after septic shock, and that a delayed increase in the expression of S100A9 was associated with hospital-acquired infections after septic shock." (PMID 24956170, 2014).
Hypoinsulinemia (2 papers, 2019 to 2022). A decreased concentration of insulin in the blood. "DT administration caused a similar degree of severe hypoinsulinemia in RIP-DTR; Tlr4−/− and RIP-DTR; Rage−/− mice and their littermate controls with intact TLR4 and RAGE, respectively, and S100A9 overexpression did not affect this parameter." (PMID 31391467, 2019).
ichthyosis (2 papers, 2016). Disorders of cornification that are characterized by visible scaling and/or hyperkeratosis of most or all of the skin. "Interestingly, we observed a significant increase in the transcripts for S100A8, S100A9, Krt1, and Saa1, which have been shown to maintain skin integrity, barrier function, inflammation, and ichthyosis in human skin." (PMID 27556734, 2016).
infectious arthritis (2 papers, 2022 to 2023). "Our data clearly show that gene expression levels of S100a8/S100a9, rather than protein levels, predict the development of septic arthritis in mice with systemic S. aureus infection." (PMID 37396347, 2023).
keratoconus (2 papers, 2020 to 2025). A degenerative, structural disorder of the eye, characterized by a cone-shaped protrusion of the cornea. "In addition, a combination of genes significantly upregulated in the KJ samples only, S100A8, S100A9, ADAMTS14, LYPD2 and AOC1 may yield distinguishing biomarkers for subtypes of keratoconus." (PMID 32555404, 2020).
liver dysfunction (2 papers, 2023 to 2024). "In contrast, treatment with the AMPK inhibitor Compound C reversed the inhibitory effects of S100A9 KO on CLP-induced liver dysfunction and injury in vivo." (PMID 36768433, 2023).
lupus erythematosus (2 papers, 2013 to 2015). An autoimmune, connective tissue chronic inflammatory disorder affecting the skin, joints, kidneys, lungs, heart, and the peripheral blood cells. "In addition, CD8+ cells from subjects with lupus erythematosus stimulated with S100A8 or S100A9 showed an upregulation of IL-17 expression, leading to the development of auto-reactive lymphocytes." (PMID 23626736, 2013).
lupus nephritis (2 papers, 2022 to 2025). Glomerulonephritis in the context of systemic lupus erythematosus. "SLE can increase the levels of S100A8, S100A9, and S100A12 in serum and the combination of the three proteins can be used as biomarkers for lupus nephritis caused by SLE." (PMID 35796625, 2022).
metastasis (2 papers, 2012 to 2021). The spread or migration of cancer cells from one part of the body (where they first appeared) to another. "Low S100A9 cell count was found to be correlated with tumor invasion depth (T stage), lymph node metastasis (N stage), and clinical TNM stage (P = 0.011, 0.009, and 0.002, respectively)." (PMID 22838504, 2012).
metastatic cancer (2 papers, 2012 to 2022). A carcinoma which has spread from the original site of growth to another anatomic site. "All examined metastatic lymph nodes (n = 30) were also positive for S100A9 with immunostaining exclusively located in inflammatory cells surrounding the metastatic cancer tissues." (PMID 22838504, 2012). "The existence of S100A9 positive macrophages in tumor tissues, a key gene in the growth and metastasis of HCC, was related to the shorter survival time and the poor treatment of PD-1 antibody in metastatic cancer patients." (PMID 36120553, 2022).
myelofibrosis (2 papers, 2023 to 2025). A partial or complete replacement of the bone marrow stroma by fibrous tissue. "We combined our murine model of TPO overexpression‐induced MPN/myelofibrosis with a knockout of S100a9 in HSPCs, and transplanted lethally irradiated WT recipients with either WT (here referred to as S100a9+/+) or S100a9−/− ckit+ HSPCs overexpressing TPO or its EV control." (PMID 40823315, 2025). "However, overexpression of S100A9 in Jak2V617F/+ mice BM did not induce myelofibrosis in transplanted animals (data not shown)." (PMID 38012156, 2023).
myeloproliferative diseases (2 papers, 2020 to 2024). "In patients with myeloproliferative neoplasms and murine models, the expression of the alarmin complex S100A8/S100A9, a crucial proinflammatory player in MPNs, in MSC mediates the disease progression toward the fibrotic phenotype." (PMID 38314300, 2024).
Neonatal sepsis (2 papers, 2024 to 2026). Systemic inflammatory response to infection in newborn babies. "Notably, S100A9 was reported to regulate the intestinal environment: Mice lacking S100A9 displayed reduced CX3CR1 protein levels, IL10 and TGF mRNA expression, and fewer T‐reg cells in intestinal tissues, accompanied by a higher risk of fatal neonatal sepsis." (PMID 41542228, 2026).
oral lichen planus (2 papers, 2022 to 2024). Oral lichen planus is a chronic inflammatory oral condition of unknown aetiology characterized by T-cell-mediated chronic immune response and abnormal epithelial keratinization cycle. "The differential expression of AMPs in oral lichen planus patients, characterized by reduced levels of S100A8 and S100A9 and increased levels of S100A7, suggests alterations in the chemical barrier that may enhance susceptibility to oral infections and inflammation." (PMID 38750317, 2024).
ovarian tumor (2 papers, 2015 to 2024). "Furthermore, it has recently been shown that tumor-derived S100A9 induced the production of IL-6 by myeloid cells in ovarian tumors, and that IL-6 drives angiogenesis with defective pericyte coverage typical for TME." (PMID 26673090, 2015). "This research confirmed that chronic stress downregulated HDC expression in ovarian tumor models, upregulating the expressions of IL-6, p-STAT3, and S100A9." (PMID 39720595, 2024).
pituitary adenomas (2 papers, 2019 to 2020). "Correlation between clinical features and the expression of S100A9 in 80 pituitary adenomas." (PMID 33203795, 2020).
Pneumocystis infection (2 papers, 2010 to 2022). "Among the genes that were affected by dexamethasone and further affected by Pneumocystis infection, Mgst1 and Hspa1b genes were down-regulated, while Cd14, Irf8, Il1b, Cxcl13, Cxcr4, Fn1, Irf1, Cd74, S100a9, and Spp1 genes were up-regulated in all four groups." (PMID 20377877, 2010). "Other DAMPs identified in the proteomics included protein S100-A8 and protein S100-A9, which were slightly increased in B cell exosomes after Pneumocystis infection, although not significantly." (PMID 35465354, 2022).
respiratory failure (2 papers, 2023 to 2024). The significant impairment of gas exchange within the lungs resulting in hypoxia, hypercarbia, or both, to the extent that organ tissue perfusion is severely compromised. "S100-A9 was a valuable marker in predicting the occurrence of postoperative liver and respiratory failure, and higher S100-A9 values indicated a reduced possibility of liver and respiratory failure." (PMID 39049003, 2024). "Patients with kidney, liver, cerebral, coagulation, circulation, and respiratory failure had elevated plasma S100A8 and S100A9 than those without these conditions, as well as those with bacterial infections." (PMID 37469934, 2023).
sarcoma (2 papers, 2022 to 2024). A usually aggressive malignant neoplasm of the soft tissue or bone. "Notably, amplification was the most common type of mutation, and S100A9, IPCEF1, and GPX7 were frequently amplified in sarcoma." (PMID 35143416, 2022).
sarcopenia (2 papers, 2025 to 2026). Progressive decline in muscle mass due to aging which results in decreased functional capacity of muscles. "Thus, Spp1 and S100a9 are associated with the molecular phenotypes of sarcopenia." (PMID 39911133, 2025). "However, the role of S100a9 in sarcopenia has not been well studied." (PMID 39911133, 2025).
Shock (2 papers, 2022 to 2025). The state in which profound and widespread reduction of effective tissue perfusion leads first to reversible, and then if prolonged, to irreversible cellular injury. "While identifying patients with septic shock, the analysis revealed that S100A9 (AUC = 0.74, 95% CI 0.68–0.79, P < 0.0001) performed similarly to Apache II but superior to lactate and PCT." (PMID 40478888, 2025). "UPP1, S100A9, KIF1B, S100A12, SLC26A8 emerge remarkable diagnostic performance in pediatric septic shock and involved in immune cells infiltration." (PMID 36439140, 2022).
spondyloarthritis (2 papers, 2016 to 2025). "Out of the eight co-expressed highly expressed proteins, S100A8, S100A9, SERPING1, CECR1, and FERMT3 are all associated with inflammation, with S100A8 and S100A9 being clinically confirmed to be closely related to spondyloarthritis." (PMID 39877611, 2025). "This further confirms the close relationship of S100A8 and S100A9 with the phenotype of this spondyloarthritis." (PMID 39877611, 2025). "S100A8 and S100A9 may be markers of spontaneous spondyloarthritis in crab-eating macaques." (PMID 39877611, 2025). "Analysis of key common proteins has revealed that the proteins with the highest expression in the spondyloarthritis group are S100A8 and S100A9." (PMID 39877611, 2025). "It is evident that the high expression of S100A8, S100A9, SERPING1, ZYZ, VCL, and FERMT3 is positively correlated with spondyloarthritis." (PMID 39877611, 2025). "Recently, serum calprotectin, a heterodimeric complex of two S100 calcium-binding myeloid-related proteins (MRP8 [or S100A8] and MRP14 [or S100A9]), has been reported to be a sensitive biomarker of disease activity in patients with RA and patients with spondyloarthritis." (PMID 27391315, 2016). "It is hypothesized that S100A8 and S100A9 could serve as potential predictive biomarkers for spondyloarthritis in non-human primates." (PMID 39877611, 2025). "It is hypothesized that S100A8 and S100A9 could serve as potential predictive biomarkers for this spondyloarthritis in non-human primates." (PMID 39877611, 2025).
staphylococcus aureus infection (2 papers, 2023 to 2025). An infectious process in which the bacteria Staphylococcus aureus is present. "Studies in mice deficient in S100a9 demonstrated protection from systemic Staphylococcus aureus infection owing to a reduced bacterial burden in the heart, suggesting a potential organ‐specific function for S100a9." (PMID 39478283, 2025). "Consistent with our result, the antimicrobial peptides S100A8, S100A9, and CATHL\H4 were highly expressed in milk exosomes after Staphylococcus aureus infection." (PMID 36611779, 2023).
synovitis (2 papers, 2020). Inflammation of a synovial membrane. "In this study, we investigated the role of S100A9 in pain response during acute synovitis." (PMID 32854769, 2020). "Although clearly present in WT and S100A9−/− mice, allodynia was equal between the two groups, excluding a role for S100A8/9 in sensitization in acute synovitis." (PMID 32854769, 2020). "Acute synovitis was induced by streptococcal cell wall (SCW) injection in the knee joint of C57Bl/6 (WT) and S100A9−/− mice." (PMID 32854769, 2020).
venous ulcer (2 papers, 2015 to 2025). "In a different study, fibronectin was shown to be elevated, but S100A8 and S100A9 were decreased in chronic venous ulcer fluids compared to acute wound fluid." (PMID 40342218, 2025).
vitiligo (2 papers, 2022 to 2024). Generalized well circumscribed patches of leukoderma that are generally distributed over symmetric body locations and is due to autoimmune destruction of melanocytes. "Multivariate logistic regression analysis showed S100B (OR, 1.019; 95% CI, 1.002-1.038; P =0.03), S100A9 (OR, 1.002; 95% CI, 1.001-1.003; P<0.001), and HMGB1 (OR, 1.915; 95% CI, 1.186-3.091; P =0.008) were significantly associated with vitiligo activity." (PMID 36569840, 2022). "Thus, we explored the association between S100B, S100A9, and HMGB1 and vitiligo severity in various disease activity phases." (PMID 36569840, 2022). "Although the diagnostic value of the combined model has a superimposed effect, the difference in actual values of S100A9 between the active and stable vitiligo patients is remarkable, indicating that the assessment of vitiligo activity based on the model with only one predictor is promising." (PMID 36569840, 2022). "Thus the exact function and intervention mechanism of S100A9 in the development of vitiligo is of great importance to be investigated." (PMID 36569840, 2022). "With the dual guarantee of multivariate logistic regression and ROC analysis, we found that serum HMGB1, S100B, and S100A9 can efficiently discriminate between patients with stable and active vitiligo, and can be used as potential biomarkers for the prediction of disease activity." (PMID 36569840, 2022). "Cluster12 keratinocyte RBP-expression groups, namely, ZC3H12A, S100A9, CYCS, and EIF5A, were also enriched in the apoptotic pathway in the patients with vitiligo." (PMID 38438962, 2024). "S100A9 and S100A12, the two alarmins are prone to rise after oxidative stress which is an important inducer for vitiligo initiation, and then involved in the aberrant immune response." (PMID 36569840, 2022). "Our ROC analysis revealed that serum IL-1α, S100B, S100A9, and HMGB1 had predictive capacity on the diagnosis of vitiligo." (PMID 36569840, 2022). "For vitiligo diagnosis, S100B had the highest sensitivity (92.31%), whereas HMGB1 had the highest specificity (85.71%); the combination of IL-1α, S100B, S100A9, and HMGB1 increased the AUC value to 0.925, with a sensitivity of 87.50% and a specificity of 85.71%." (PMID 36569840, 2022). "More importantly, S100A9 is highly expressed and easily measured in serum samples, with expression levels hundreds of times higher than soluble CDs and chemokines such as CXCL10, thus might be expected to be one of the most valuable biomarkers of vitiligo activity." (PMID 36569840, 2022). "Therefore, in this study we would like to detect the serum expression of these alarmins (HMGB1, S100B, IL-1α, IL-33, S100A9, and S100A12) in NSV patients and healthy controls, to further investigate their clinical significance in the diagnosis and assessment of disease activity/severity in vitiligo." (PMID 36569840, 2022).
Warthin tumor (2 papers, 2013 to 2024). An adenoma characterized by an oncocytic, often papillary, epithelial component, dense lymphoid stroma, and cystic spaces. "On the other hand, the protein network detected in Warthin’s tumors (e.g., IGHG1, IGKC, IGHA1, and S100A9) was associated with immunological and inflammatory diseases." (PMID 39684268, 2024).